RNU6-930P (RNA, U6 small nuclear 930, pseudogene)
Synonyms: RNU6-1173P
Gene: Small nuclear RNA gene on chromosome 6 (28,915,645 to 28,915,744, forward strand). Ensembl gene ENSG00000212240.
Homologues: Orthologues: chimpanzee U6 (100% identical), macaque U6 (95% identical), mouse Gm23506 (81% identical), pig U6 (78% identical), guinea pig U6 (73% identical), rabbit U6 (73% identical). Paralogues in human: RNU6-487P (83% identical), RNU6-1103P (82% identical), RNU6-1251P (81% identical), RNU6-16P (81% identical), RNU6-33P (81% identical), RNU6-480P (81% identical), RNU6-1 (80% identical), RNU6-1060P (80% identical), RNU6-1145P (80% identical), RNU6-116P (80% identical), RNU6-15P (80% identical), RNU6-2 (80% identical), and 1287 more.